SUNO1 (S-phase upregulated non-coding 1)
Gene: Long non-coding RNA gene on chromosome 19 (33,906,352 to 33,908,393, forward strand). Ensembl gene ENSG00000277013.
Diseases named in the same sentence as SUNO1 in open-access papers:
SUNO1 is named in the same sentence as 6 diseases in open-access papers, as found by Europe PMC text mining. Sharing a sentence is not in itself a finding about the gene and the disease. The quoted sentences say what the papers report.
colon carcinoma (2 papers, 2020 to 2022). "Next, we tested whether the ~149 genes that showed reduced expression in SUNO1-depleted cells also exhibited synchronous change in expression patterns in the TCGA colon cancer patient cohort." (PMID 33108271, 2020). "Interestingly, a major fraction of these genes (71%), including WTIP, showed positive correlation in expression with SUNO1 across colon cancer patients, implying that SUNO1 potentially regulates the expression of these genes even in cancer tissue samples." (PMID 33108271, 2020). "SUNO1 affects DDX5 to regulate the recruitment of RNA polymerase II to a the WTIP cis promoter, enhancing the transcription of WTIP, and promoting the development of colon cancer." (PMID 35992805, 2022).
breast carcinoma (1 paper, 2020). "For example, the tumorigenic human breast cancer cell line BT-20 showed the highest expression of SUNO1, whereas HCT116 and U2OS showed moderate levels of SUNO1 compared to other cell lines, such as the WI-38 human diploid fibroblasts." (PMID 33108271, 2020).
colon adenocarcinoma (1 paper, 2020). "(C) Spearman correlation of the expression levels of YAP1/TAZ/TEAD target genes with SUNO1 in colon adenocarcinoma patient tumor samples." (PMID 33108271, 2020). "Our hypothesis is supported by the observation that elevated expression of SUNO1 correlates with poor prognosis in colon adenocarcinoma, and further tumor assays revealed that SUNO1 is required for the tumorigenicity of colon cell lines." (PMID 33108271, 2020).
gastric cancer (1 paper, 2023). A primary or metastatic malignant neoplasm involving the stomach. "For example, lncRNA SUNO1 promotes cell cycle progression by controlling the YAP1/Hippo signaling pathway; miR-218 suppresses gastric cancer cell cycle progression via the CDK6/Cyclin D1/E2F1 axis." (PMID 37538116, 2023).
cancer (1 paper, 2020). A tumor composed of atypical neoplastic, often pleomorphic cells that invade other tissues. "Finally, elevated SUNO1 levels are associated with poor cancer prognosis and tumorigenicity, implying its pro-survival role." (PMID 33108271, 2020).
tumor (1 paper, 2020). "Further, to test the involvement of SUNO1 in tumor progression, we performed anchorage-independent growth assays in wild-type and SUNO1-KO HCT116 cells." (PMID 33108271, 2020). "We next performed tumor xenograft assay to examine the effect of SUNO1 deletion on primary tumor growth in vivo." (PMID 33108271, 2020). "The tumor growth in SUNO1-KO cells was significantly compromised compared to control HCT116 cells." (PMID 33108271, 2020). "SUNO1-KO HCT116 and control HCT116 cells were injected subcutaneously into the flanks of immune compromised mice, and the tumor sizes were monitored for 25–30 days post-injection." (PMID 33108271, 2020).